MAPT (microtubule associated protein tau)
Diseases named in the same sentence as MAPT in open-access papers (continued):
Sharing a sentence is not in itself a finding about the gene and the disease.
dementia (continued). "While the presence of tau pathology has been correlated with reduced time to dementia, some evidence also supports that the MAPT H1-haplotype may influence the cortical LB burden, suggesting MAPT also may promote dementia in more than one way." (PMID 33613437, 2021). "We included 106 presymptomatic and 54 symptomatic carriers of a pathogenic mutation in GRN, C9orf72 or MAPT, and 70 healthy non-carriers participating in the Genetic Frontotemporal dementia Initiative (GENFI), all of whom had at least one CSF sample." (PMID 32273328, 2020). "We aimed to investigate mutation‐specific white matter (WM) integrity changes in presymptomatic and symptomatic mutation carriers of the C9orf72,MAPT, and GRN mutations by use of diffusion‐weighted imaging within the Genetic Frontotemporal dementia Initiative (GENFI) study." (PMID 30250860, 2018). "For MAPT, the H1 haplotype has been associated with cognitive decline or dementia in some but not all PD studies." (PMID 28520803, 2017). "Given the frequency of variants identified in MAPT, GRN and C9ORF72, but also in our previous analysis of PSEN1, PSEN2 and APP, in the Turkish cohort of dementia patients studied, a standardized molecular screening procedure for these genes should be implemented in Turkey." (PMID 27632209, 2016). "Obvious polymorphic targets in dementia could include apolipoprotein E (APOE) and microtubule-associated protein τ (MAPT), given their known association with AD and α-synuclein related disorders." (PMID 25478032, 2014). "The implication of such hormone signals in the pathology of dementia is supported by the evidence that phosphorylation of MAPT, which leads to neurofibrillary tangle formation and ultimately neurodegeneration, is regulated by the signaling effects of insulin and estradiol." (PMID 23885764, 2013). "The identification of MAPT mutations in inherited frontotemporal dementia and parkinsonism linked to chromosome 17 (FTDP-17T) has established that dysfunction of tau protein is sufficient to cause neurodegeneration and dementia." (PMID 22496848, 2012). "However, this correlation was observed not only in presymptomatic and symptomatic carriers of mutations (including MAPT mutations) but also in noncarriers in a large cohort from the Genetic Frontotemporal Dementia Initiative (GENFI) study." (PMID 36707904, 2023). "In the Genetic Frontotemporal Dementia Initiative (GENFI), only symptomatic GRN mutation carriers were found to have an increased global load of WMH when compared to normal controls, presymptomatic GRN mutation carriers, and both presymptomatic and symptomatic C9orf72 and MAPT mutation carriers." (PMID 34256835, 2021). "Interestingly, the MAPT H1-haplotype has also been reported to be associated with an accelerated rate of cognitive decline and earlier development of dementia in PD patients, yet larger studies have not been able to replicate this finding." (PMID 33613437, 2021). "Besides the negative effect of MAPT mutations on CNS, the deposition of Amyloid-β (Aβ) plaques has also indicated its undesirable correlation with the severity of dementia, AD, PD, and even HD." (PMID 32466129, 2020). "When these data is combined with data we have previously published we conclude that among 105 dementia patients, 5.7% are attributable to PSEN1 mutations (6/105), 2.9% (3/105) to C9ORF72 and TREM2 each, and 0.95% (1/105) to MAPT, GRN and NOTCH3 each, while 85.7% (90/105) remain unclear." (PMID 27632209, 2016). "Therefore we investigated whether MAPT, GRN and C9ORF72 gene mutations are major contributors to dementia in a random, unselected Turkish cohort of dementia patients." (PMID 27632209, 2016). "Our results suggest that the MAPT locus lies at the crossroads between SIN deficits and AD-related dementia." (PMID 38849415, 2024). "As mentioned in the Results section, this second cluster includes genes that have also been related to other dementia types (e.g., GRN, TMEM107B, SNX1, MAPT, CTSB and CTSH)." (PMID 36066633, 2022).
dementia (continued). "In this work we establish the significance of the APOE, GBA, MAPT, and SNCA loci on global cognitive decline and the development of dementia over the natural course of PD in the Parkinson’s Incidence Cohorts Collaboration (PICC)." (PMID 35106798, 2022). "In this study we explored the genetic effects of MAPT and APOE on onset of dementia in PD in a neuropathologically characterized cohort." (PMID 33613437, 2021). "Several of the connections we found in our network analysis, such as GSK3B, MAPT, ADAM17, and PSEN1 are also involved in other dementias than AD." (PMID 31797941, 2019). "Since dementia is uncommon in patients with PART, the finding of p-MAPT-related axonal damage in the fornix highlights the potential importance of in vivo Aβ imaging and biomarkers to differentiate patients with AD who are more likely to progress to dementia." (PMID 27793193, 2016). "Since most of the identified proteins are not present in both diseases, we performed two independent PPI analyses: the first using the proteins associated with HF (NPPB, REN, ADIPOQ, VWF, ACE, IL6, and CRP) and the second using the proteins involved in dementia (CRP, APP, MAPT, APOE, ACE, and IL6)." (PMID 40699836, 2025). "PD MAPT H1/H1 carriers without dementia exhibited hypometabolism in the frontal cortex, parahippocampal, and cingulate gyrus, in the caudate and globus pallidus, and worse performance in attention than MAPT H1/H2 carriers." (PMID 38203667, 2023). "All MAPT carriers with dementia showed temporal atrophy, but otherwise, there was no single cognitive test or brain region that was abnormal in all subjects." (PMID 31784375, 2020). "MAPT, GRN and C9ORF72 pathogenic mutations are not uncommon in our population with different types of dementia (5.4%, 5/93)." (PMID 27632209, 2016). "To investigate this intriguing hypothesis, we analyzed rare coding variability in 6 Mendelian dementia genes (APP, PSEN1, PSEN2, GRN, MAPT, and PRNP), in 141 LOAD patients and 179 elderly controls, neuropathologically proven, from the UK." (PMID 25104557, 2014). "•We have used exome sequencing to investigate rare coding variability in Mendelian dementia genes (APP, PSEN1, PSEN2, GRN, MAPT, and PRNP) in a cohort composed of 141 late-onset sporadic Alzheimer's disease cases and 179 elderly controls, autopsy proven from the UK." (PMID 25104557, 2014). "GWASs have shown that common noncoding variability in Mendelian dementia genes (APP, PSEN1, PSEN2, MAPT, GRN, and PRNP) does not influence susceptibility to AD." (PMID 25104557, 2014). "Thus, we screened 6 Mendelian dementia genes (APP, PSEN1, PSEN2, MAPT, GRN, and PRNP) aiming to establish whether rare coding variability in these genes is responsible for an appreciable portion of the LOAD risk." (PMID 25104557, 2014). "Other studies have assessed the role of LRRK2, MAPT and SNCA for dementia in PD but results have often been inconclusive or not replicated independently." (PMID 34992521, 2021).
Parkinsonism (122 papers, 2004 to 2025). Characteristic neurologic anomaly resulting from degeneration of dopamine-generating cells in the substantia nigra, a region of the midbrain, characterized clinically by shaking, rigidity, slowness of movement and difficulty with walking and gait. "Studies described a significant association of MAPT H1j subhaplotype with PD risk, while H2 haplotype was associated with Parkinsonism, particularly to its bradykinetic component." (PMID 33343949, 2020). "In previous reports, parkinsonism and Richardson syndrome have been described in association with MAPT pathogenic variants,25, -, 27 but in our overall cohort, motor signs of a PSP-MP, PD-MP, and CBS-MP occurred most frequently in c9orf72 followed by GRN pathogenic variant carriers." (PMID 35948443, 2022). "Our research has identified patients with MAPT N279K or p.K298_H299insQ from patients with middle-aged onset of parkinsonism or those clinically diagnosed with familial PD." (PMID 35720097, 2022).
progressive supranuclear palsy (99 papers, 2010 to 2026). A rare late-onset neurodegenerative disease characterized by supranuclear gaze palsy, postural instability, progressive rigidity, and mild dementia. "The MAPT (tau) locus was first associated with PD in 2009, AD in 2015, and progressive supranuclear palsy (PSP) in 2018." (PMID 37328865, 2023). "Progressive Supranuclear Palsy (PSP) is a neurodegenerative disorder characterised by intracellular aggregation of the microtubule-associated protein tau." (PMID 25402454, 2014). "Although H1 has been reported to be overrepresented in Caucasian cases of progressive supranuclear palsy and sporadic PD, the association with MAPT per se is unclear." (PMID 24278740, 2012). "In contrast to MAPT, Richardson syndrome is rarely seen in cases with GRN mutations." (PMID 40722695, 2025). "MAPT is a gene responsible for encoding tau protein, and has been presumed to play a crucial role in pathogenesis of neurodegenerative disorders, including frontotemporal dementia, AD, progressive supranuclear palsy, and PD." (PMID 36906575, 2023). "This occurs sporadically in FTLD-tau diseases such as Pick’s disease (PiD) and progressive supranuclear palsy (PSP), or due to a genetic mutation in MAPT, the gene encoding for tau (FTLD-MAPT)." (PMID 37703311, 2024). "Microtubule-associated protein tau (MAPT) aggregates in neurons, astrocytes and oligodendrocytes in a number of neurodegenerative diseases, including progressive supranuclear palsy (PSP)." (PMID 37354322, 2023). "Testing for association of CBD with top progressive supranuclear palsy (PSP) GWAS single-nucleotide polymorphisms (SNPs) identified associations at MOBP (3p22; rs1768208; P=2.07 × 10−7) and MAPT H1c (17q21; rs242557; P=7.91 × 10−6)." (PMID 26077951, 2015). "For example, accumulation of hyperphosphorylated tau aggregates occurs in Alzheimer’s disease (AD), sporadic Pick’s disease (PiD), corticobasal degeneration (CBD), and progressive supranuclear palsy (PSP) in the absence of MAPT mutations." (PMID 39880096, 2025). "As a control, we performed the same analysis using >350 randomly selected SNPs from the MAPT locus implicated in progressive supranuclear palsy, a condition not expected to involve the RPE." (PMID 40196652, 2025). "Progressive supranuclear palsy (PSP) describes a spectrum of fatal motor and behavioural syndromes which are characterised by the neuronal and glial accumulation of 4 repeat-domain containing isoforms of the microtubule associated protein tau (4R-tau)." (PMID 36498882, 2022). "Tauopathies include frontotemporal lobar degeneration (FTLD) with tau positive inclusions with or without gene mutation in MAPT, Pick disease, progressive supranuclear palsy, corticobasal degeneration, and others." (PMID 33643196, 2021). "The PSP syndrome has been reported in patients with damaging mutations in MAPT, but there are only a few autopsy-proven cases of familial PSP due to MAPT mutations, including two brothers with early-onset PSP and a MAPT p.S285R mutation." (PMID 34425874, 2021). "Surprisingly, however, we found that PAOS-PSP had a lower frequency of the H1 allele compared to PAOS-CBD and also compared to our large pathologically-confirmed cohort with typical Richardson’s syndrome, suggesting the MAPT H1 allele may not be a risk for PAOS-PSP." (PMID 34103532, 2021). "Searching for other cases resulted in the identification of PSEN1 p.A79V in one possible AD patient, PSEN1 p.R269H and MAPT p.A60G in two independent MCI patients, and GBA1 p.W223R and APP p.A209T in two independent progressive supranuclear palsy (PSP) patients." (PMID 40813364, 2025).
Cognitive impairment (60 papers, 2012 to 2025). Abnormal cognition is characterized by deficits in thinking, reasoning, or remembering. "Overall, the MAPT mutation is associated with the least severe cognitive impairment among the three genetic subtypes, with global cognitive functioning largely preserved and notable deficits confined to specific areas, such as abnormal behaviour." (PMID 40649976, 2025). "Regarding the impact of CNV mutations in the MAPT gene on cognitive impairment, a statistically significant association with the MoCA delay recall was found for exon 2 (p = 0.014) and with the MoCA total score for exon 8 (p = 0.033)." (PMID 40725212, 2025). "The results indicate that carriers of C9orf72seq, GRN, and MAPT mutations exhibit a significant global cognitive impairment compared to healthy controls." (PMID 40649976, 2025). "Explorations of the risks underlying cognitive impairment in PD have implicated, among other entities, the microtubule-associated protein tau (MAPT) H1 haplotype." (PMID 37214541, 2023). "MAPT H1 is also associated with the ApoE-4 allele and leads to faster progression from mild cognitive impairment to dementia in patients with both alleles." (PMID 36361631, 2022). "PS19 mice expressing the MAPT P301S mutation, for example, progressively develop pathogenic tau species, neuronal loss and cognitive impairments." (PMID 35682712, 2022). "To date, cognitive impairments, including memory, executive functioning, visuo-construction, language, and behavioral changes have been associated with tau pathology or MAPT mutation, while social cognition impairments were found in patients with C9orf72." (PMID 35992608, 2022). "Similarities were seen between CBS patients with PRNP and MAPT mutations, with high recurrence in extrapyramidal symptoms, dystonia, oculomotor and bulbar dysfunction, cognitive impairment, and alien-limb phenomena." (PMID 33467748, 2021). "Genetic variation impacts the age of onset and disease risk, with SNCA and MAPT genes contributing to progression and cognitive impairment." (PMID 31033450, 2019). "Relatively few studies examined the MAPT H1 haplotype as a risk factor for cognitive impairment in PD." (PMID 30155299, 2018). "Phosphorylated microtubule-associated protein tau (tau) aggregates are a pathological hallmark of various neurodegenerative diseases, including chronic traumatic encephalopathy and amyotrophic lateral sclerosis with cognitive impairment." (PMID 38026695, 2023). "Similarly, misfolding of microtubule-associated protein tau (MAPT) into neurofibrillary tangles (NFTs) also correlates with cognitive deficits in AD." (PMID 30227881, 2018). "In addition, the rs17651507 variant in MAPT has been associated with waist–hip ratio, which could be in agreement with data showing a connection between cognitive impairment and obesity." (PMID 37372445, 2023). "Several associations between CNV mutations in genes (APP, GRN, MAPT, PSEN1, PSEN2) and various domains of cognitive impairment were identified." (PMID 40725212, 2025). "A detailed statistical analysis of the different exons of the PSEN1, MAPT, and GRN genes in relation to the significantly associated cognitive impairment domains was conducted based on MoCA data." (PMID 40725212, 2025). "MAPT mutation carriers show lower scores on both MMSE and MoCA, with significant global cognitive impairment, although this is generally less severe than in GRN carriers." (PMID 40649976, 2025). "We identified associations with cognitive impairment specifically in the CNV mutations of the PSEN1 (exons 1, 9, 12), GRN (exons 1, 6, 12), and MAPT (exons 2, 8) genes." (PMID 40725212, 2025). "Other models like the 3xTg mice carrying the AD-associated APP-Swedish, MAPT-P301L and PSEN1-M146V mutations demonstrate formation of Aβ plaques and neurofibrillary tangles along with neuroinflammation, synaptic dysfunction, cognitive impairment." (PMID 38450383, 2024).
Cognitive impairment (continued). "For instance, PTGS2, MAPT, and GABRA1 are critical targets of leukodystrophy and are associated with AD, neuropathic pain, and cognitive impairment in the T-D network." (PMID 36500385, 2022). "We describe 2 novel MAPT mutations, D252V and G389_I392del, each presenting in a patient with behavioral variant FTD and associated language and cognitive deficits." (PMID 31870644, 2020). "Recently, substantial work has focused on phospho-tau/MAPT (p-MAPT) neuropathology since its regional propagation correlates with the degree of cognitive impairment in AD." (PMID 27793193, 2016). "This resulted in the induced transcription and expression of APP, MAPT (coding for the microtubule-associated protein Tau), LGMN (coding for δ-secretase) and inflammatory cytokines, escalating AD-related gene expression and pathogenesis and resulting in AD pathology and cognitive disorder." (PMID 37047617, 2023). "MAPT plays an important role in promoting microtubule assembly and stabilizing microtubules, and the accumulation of its hyperphosphorylation induces synaptic toxicity and cognitive impairment." (PMID 37801512, 2023). "A robust argument that could explain the association of PRS with cognitive deficit in pPD is that many genes that are included in PRS such as GBA, SNCA and MAPT, have been linked with cognitive outcomes in PD separately." (PMID 34992521, 2021). "Along with pathogenic mutations, genetic variants in at least 3 genes, apolipoprotein E (APOE), microtubule-associated protein tau (MAPT), and α-synuclein (SNCA), might play a role in determining susceptibility to cognitive impairment in PD." (PMID 35003622, 2021). "Mutations in the MAPT gene have been associated with neurodegenerative diseases such as Frontotemporal dementia, PSP and AD; diseases characterized by abnormal accumulation of pathological forms of tau and that further correlate with cognitive deficits." (PMID 33329322, 2020). "Several studies, however, report that MAPT−/− mice are resistant to some functional and cognitive deficits after TBI, although this depends on whether the injury was repetitive and whether short-term or long-term outcomes were measured." (PMID 32728795, 2020). "Recent advances include the generation of a tau knockout mouse (tauΔex1) line using CRISPR/Cas9 targeting the MAPT gene, which overcame the limitations of earlier embryonic stem cell-based models and exhibited reduced seizure susceptibility without cognitive impairment." (PMID 40869138, 2025). "This could explain why MAPT mutation carriers do not exhibit the same breadth of cognitive impairments seen in C9orf72seq or GRN mutations." (PMID 40649976, 2025). "Since cognitive impairment in AD is correlated with the spread of pathologic tau, it is possible that the risk of progression from MCI to AD might be predicted by the spread of p-MAPT from the hippocampus via the fornix." (PMID 27793193, 2016). "Over the last years, following and thanks to the genetic discoveries in the MAPT gene, striking observations in patients but mainly in experimental models have changed some long-established convictions concerning the role of protein Tau in cognitive disorders and neurodegeneration." (PMID 22720188, 2012). "In addition to documented pathogenic mutations in PD genes, common genetic variants in at least three genes, apolipoprotein E (APOE), microtubule-associated protein tau (MAPT), and α-synuclein (SNCA), may play a role in the eventual susceptibility to cognitive impairment in PD patients." (PMID 40722695, 2025). "In the context of subarachnoid hemorrhage (SAH), a type of cerebral bleed leading to severe brain damage and often resulting in cognitive impairment, studies have found that nimodipine can ameliorate cognitive impairment post-SAH in rats via the lncRNA NEAT1/Mir-27a/MAPT axis." (PMID 38543885, 2024).
Cognitive impairment (continued). "Whether or not linked to mutations in the MAPT gene, the clinical features of the frontotemporal lobar degeneration (FTLD) spectrum are generally dominated by motor and emotional/psychiatric abnormalities, whilst cognitive deficits tend to be rarer, more subtle and present at later disease stages." (PMID 25523019, 2015).